IL18 (interleukin 18)
Diseases named in the same sentence as IL18 in open-access papers (continued):
Sharing a sentence is not in itself a finding about the gene and the disease.
Hyperglycemia (continued). "Previous studies have demonstrated that hyperglycemia activates the innate immune response mediated by TLR2, TLR4, and the NLRP3 inflammasome, inducing the production of various proinflammatory cytokines, including IL-1β, IL18, IL-6, and TNFα." (PMID 34356130, 2021). "In an excellent agreement, the present data revealed that hyperglycemia could induce the activation of the NLRP3 inflammasome and ultimately lead to the increased expression of IL-1β and IL-18." (PMID 31178664, 2019). "IL-18 KO mice had higher food intake and greater increase in body weight without significant differences in hyperglycemia." (PMID 28394363, 2017). "If we accept the possibility that CAN may have increased GRO-KC, IL-18, and TGF-β1 as a result of relative hyperglycemia in these rats, what was the mechanism for the impaired GTT?" (PMID 20490358, 2010). "In addition, oscillatory hyperglycemia as routinely found in most patients, causes more acute increases in plasma concentrations of pro-inflammatory cytokines including IL-6, IL-18, and TNF-α, as compared to chronic hyperglycemia." (PMID 21629436, 2010). "Furthermore, Hyperglycemia could also increase inflammatory cytokine (including tumor necrosis factor‐α [TNF‐α], interleukin‐6 [IL‐6], and interleukin‐18 [IL‐18]) by an oxidative stress mechanism in human, suggesting hyperglycemia triggers inflammatory response." (PMID 32697441, 2020).
Hypertension (61 papers, 2013 to 2025). The presence of chronic increased pressure in the systemic arterial system. "We found strong correlations between hs-CRP, adiponectin, chemerin, and IL-18 with risk factors for cardiometabolic syndrome, including abdominal obesity, hypertension, low HDL, and poor overall cardiometabolic health." (PMID 39940942, 2025). "IL-1β and IL-18 concentrations are elevated in the circulation of patients with essential hypertension, and this increase is associated with elevated blood pressure." (PMID 40572711, 2025). "While the usefulness of IL-1β as a therapeutic target for hypertension remains controversial, IL-18 levels in the blood were associated with higher blood pressure." (PMID 38256155, 2024). "IL-18 gene promoter -137 G/C polymorphism was also associated with an increased risk of sudden cardiac death in the context of hypertension." (PMID 38256155, 2024). "A high IL-18 level was significantly associated with a higher frequency of hypertension, lower left ventricular ejection fraction (LVEF), and higher frequency of statin use." (PMID 36499595, 2022). "A recent study found a direct association between IL-18 and kidney damage during deoxycorticosterone/salt-induced hypertension in mice." (PMID 35269384, 2022). "IL-1β and IL-18 are associated with hypertension and hypertensive patients exhibit enhanced levels of IL-1β." (PMID 33494430, 2021). "Some authors reported that patients with a genetic predisposition to a higher IL-18 concentration have a higher risk of arterial hypertension, ischemic heart disease and its complications." (PMID 34571700, 2021). "We previously demonstrated in patients with hypertension an association between left ventricular maladaptation and plasma IL-18." (PMID 33066786, 2020). "We further investigated the association between IL-18 -607A/C gene polymorphism and BMI, hypertension, smoking and drinking on the risk of IS (Table-III)." (PMID 25878643, 2015). "Stratified analysis showed that an increased risk of IS was associated with those carrying IL-18 -607AC+CC, even in those with higher BMI, hypertension, smoking and drinking habits." (PMID 25878643, 2015). "In addition, TNFα causes kidney damage in angiotensin-II-dependent hypertension and enhances IL-18 gene expression." (PMID 35269384, 2022). "Similarly the inflammasome was shown to be involved in cardiac arrhythmias, and higher levels of IL-1β and IL-18 have been associated with hypertension." (PMID 33149733, 2020). "This hypertension model is associated with inflammation in the kidney, and the NLRP3/IL1β/IL-18 signaling system is involved." (PMID 39576390, 2025). "Activation of NLRP3 in the placenta, uterus, kidneys, and maternal endothelium leads to the production of pro-inflammatory cytokines (IL-1β and IL-18) and triggers processes such as endothelial dysfunction, sodium retention, and hypertension." (PMID 40867825, 2025). "In a Turkish adult study, interleukin-18 was not only higher in patients with newly diagnosed hypertension compared to the control group, but its concentration was strictly related to the non-dipping pattern." (PMID 40869561, 2025). "Evidence suggests that IL-1β and IL-18 levels in blood and vascular tissues are elevated in hypertension." (PMID 40572711, 2025). "Compared with normal people, the levels of serum IL-1β and IL-18 are higher in patients with hypertension." (PMID 35668772, 2022). "Secondary bile acids such as lithocholic acid and deoxycholic acid reduce the risk of hypertension by being farnesoid X receptors and TGR5 agonists, the regulation of inducible nitric oxide synthase, IL18, and angiogenin pathways." (PMID 36557936, 2022). "Putrescine and spermine roles in hypertension include protection against inflammation via the inhibition of caspase-1 and secretion of IL-18." (PMID 36557936, 2022). "MALAT1 enhances the levels of proinflammatory cytokines (IL-18 and IL-1β) in pregnancy-induced hypertension by activating the NF-κB pathway." (PMID 35626352, 2022).
Hypertension (continued). "The findings of the present study revealed a direct relation between age (above 45 years for men and 55 years for women) and hypertension, and elevated IL-18 levels." (PMID 31516856, 2019). "The NLRP3 inflammasome, a key signaling platform that activates highly proinflammatory cytokines, IL-1β and IL-18, contributes to the development of aortic aneurysms and hypertension via vascular inflammation." (PMID 30906225, 2019). "It was found that serum level of IL-18 was higher in older people (men over 45 and women over 55 years old) and participants with hypertension." (PMID 31516856, 2019). "And NLRP3 inflammasome was involved with CaSR-mediated fibrosis during hypertension, which led to IL-1β and IL-18 release." (PMID 30906225, 2019). "IL-1β and IL-18, the inflammasome-induced cytokines play critical roles in hypertension and inhibition of IL-1β has shown potential in reducing blood pressure and preventing the development of hypertension." (PMID 40433411, 2025). "The produced ROS leads to activation of the NLRP3 inflammasome, resulting in activation of caspase-1, cleavage of pro-IL-1β and pro-IL-18, and the production of active forms of IL-1β and IL-18, which increase the inflammatory response, fibrosis, and vascular remodeling in hypertension." (PMID 40227195, 2025). "Thus, extensive studies are needed to discern the true therapeutic potential of IL-18 targeting in hypertension." (PMID 38256155, 2024). "Furthermore, elevated IL‐18 levels were linked to an increased risk of adverse clinical events among participants with a history of hypertension when IL‐18 was used as a dichotomous variable (p ≤ 0.05)." (PMID 38402570, 2024). "Notably, new studies involving pro-inflammatory interleukin IL-18 and anti-inflammatory interleukins IL-37 and IL-38 have provided interesting new findings related to hypertension prevention." (PMID 34445357, 2021). "Different studies revealed that polymorphisms in the IL-1β gene are associated with higher blood pressure in ethnic populations; however, the question still remains whether IL-1β and IL-18 are inflammatory markers or mediators of hypertension in humans." (PMID 33494430, 2021). "Elevated activation levels of the key NLRP3 inflammasome priming factor, NF-κB, in tissue and inflammatory cells are persistent in hypertension and result in exaggerated levels of circulating and tissue IL-1β and IL-18 in patients with essential hypertension and in animal models of the disease." (PMID 33494430, 2021). "In this model, it is speculated that CaSR activation in VSMCs increases cytosolic [Ca2+]i, which stimulates NLRP3 inflammasome activation and leads to IL-1β and IL-18 maturation during hypertensive aortic fibrosis." (PMID 30906225, 2019). "The protective effects of IL-18 -607 genotypes on the risk for RCC appeared to be obvious among people with or without hypertension." (PMID 30925760, 2019). "Multivariate Cox regression analysis showed that low serum albumin, the presence of hypertension, high serum IL-18, and less negative GLS (>−15%) were independently associated with all-cause mortality." (PMID 24599060, 2014). "In contrast, the levels of IL-18 and chemerin, although elevated in subjects with all metabolic abnormalities, only showed statistically significant increases in participants with specific abnormalities, namely high blood pressure, high triglycerides, and low HDL cholesterol (q < 0.05)." (PMID 39940942, 2025). "Previous research has predominantly examined specific clinical biomarkers linked to AKI in hypertension and other conditions, including neutrophil gelatinase-associated lipocalin (NGAL), kidney injury marker 1 (KIM-1), cystatin C (CysC), ST2, interleukin 18 (IL-18), and albuminuria." (PMID 39072271, 2024).
Hypertension (continued). "Moreover, recent studies provide compelling evidence that the NLRP3 inflammasome plays a pivotal role in sodium reabsorption in the renal tubules and may thereby contribute directly to the pathogenesis of hypertension through the action of its downstream pro-inflammatory cytokines, IL-1 and IL-18." (PMID 40867825, 2025). "Jiaodavirus was positively correlated with proinflammatory activity (IL-18, IL-10, MCP-1), IR (HOMA-IR and insulin levels), and hypertension (DBP percentile)." (PMID 37342535, 2023). "IL-18 is a proinflammatory cytokine elevated in the serum or urine of patients with CKD and hypertension." (PMID 35269384, 2022). "IL-1β and IL-18 are products of activated NLRP3 inflammasome; therefore, its role in the development of hypertension was investigated." (PMID 32650532, 2020). "Previous studies have reported that proinflammatory cytokines, IL-1β and IL-18, downstream targets of NLRP3 inflammasome, participate in the pathophysiology of cardiovascular disease and hypertension." (PMID 30906225, 2019). "Also, IL-18 stimulates ROS production from mechanical stress mediated NADPH oxidase and accentuates superoxide-induced HTN, suggesting a role in Ang II induced hypertension." (PMID 31186952, 2019). "For the stable hemodialysis patients, decreased albumin level, hypertension, increased serum IL-18 level, and less negative GLS were the independent prognostic predictors." (PMID 24599060, 2014). "The adjusted ORs for carriers with genotypes AC and CC at IL-18 -607 were 0.39 and 0.24 among subjects without hypertension (95% CI = 0.18–0.81 and 0.11–0.69, respectively) and 0.41 and 0.39 among those with hypertension (95% CI = 0.26–0.84 and 0.18–0.94, respectively), respectively." (PMID 30925760, 2019). "Immunofluorescence and western immunoblot analyses revealed that hypertension contributed to the activation of TLR4 and NF-κB, accompanied by significantly enhanced expression of proinflammatory mediators, such as tumor necrosis factor-α (TNF-α), interleukin-1β (IL-1β), and interleukin-18 (IL-18)." (PMID 24223475, 2013).
inflammatory bowel disease (61 papers, 2013 to 2026). A spectrum of small and large bowel inflammatory diseases of unknown etiology. "ITGA2B, F2RL3, PTGS1, and ADCY5 were associated with the platelet activation pathway, while IL18 was linked to inflammatory bowel disease (IBD) and the cytokine–cytokine receptor interaction pathways." (PMID 41157169, 2025). "Altered IL-18 levels are present in patients with inflammatory bowel disease and IL-18 deficient mice are showed decreased intestinal damage following experimental NEC." (PMID 32133331, 2020). "Outside of acute illness, higher IL-18 levels have been associated with chronic conditions such as heart failure, diabetic nephropathy, and inflammatory bowel disease." (PMID 24555158, 2013). "Interestingly, IL-18 bp has been found to be up-regulated during active Crohn’s disease, an inflammatory bowel disease in humans with potential association to M. paratuberculosis infection." (PMID 30323794, 2018). "This receptor has been largely associated with inflammatory diseases, including inflammatory bowel diseases, and it can signal through caspase-1 to cause the production of pro-inflammatory IL-1β and IL-18, as well as TNF-α and nitric oxide, from inflammatory cells." (PMID 29167643, 2017). "In contrast, IL18, associated with the inflammatory bowel disease (IBD) signaling pathway, was reduced in SYN-treated CIE dogs." (PMID 40563358, 2025). "MR analyses supported a causal role for IL-18 in inflammatory bowel disease (IBD) (P = 1.17 × 10−4) and eczema/dermatitis (P = 2.81 × 10−3), as well as associations between IL-2rα and IL-6R with several other IMDs." (PMID 31276585, 2019). "In humans, IL-18 is produced by gut epithelial cells and macrophages and this production is increased during inflammatory bowel diseases validating the use of anti-IL-18 monoclonal antibody for Crohn’s disease (ongoing clinical trial NCT03681067)." (PMID 41480237, 2026). "Increased levels of IL‐18 have been documented in inflammatory bowel disease, especially Crohn's disease (CD)." (PMID 40453734, 2025). "IL-18`s established role in mucosal immunity, particularly in inflammatory bowel disease, further supports its potential relevance in abdominal infections." (PMID 40510342, 2025). "Elevated levels of IL-18 and correlations to diseases activity are reported in rheumatoid arthritis, lupus erythematosus, Wegener’s disease, inflammatory bowel diseases, and cardiac diseases and most recently also in Kaposi sarcoma herpes-associated diseases." (PMID 39769266, 2024). "Numerous clinical trials assessed direct inhibition of IL-18 in B-cell non-Hodgkin’s lymphoma and inflammatory bowel disease (IBD)." (PMID 33534121, 2021). "In either case, it seems likely that the role of IL18 in inflammatory bowel disease and leprosy involve different aspects of IL18 function." (PMID 34879060, 2021). "Many proinflammatory cytokines, including IL-18, play important roles in exaggerating the disease progression of inflammatory bowel disease (IBD)." (PMID 31428451, 2019). "The pro-inflammatory role of IL-18 in inflammatory bowel disease (IBD) has been supported by studies in patients with IBD." (PMID 31428451, 2019). "Intestinal expression of IL-1β and IL-18 is enhanced in inflammatory bowel disease (IBD) patients and blocking or deleting IL-18 can reduce intestinal damage in mice." (PMID 26053862, 2015). "The Genomics England R15 primary immunodeficiency and monogenic inflammatory bowel disease gene panel of 429 genes did not reveal any pathogenic variants, including genes known to be associated with high IL-18 levels and inflammation such as NLRC4 or XIAP." (PMID 39458007, 2024). "In addition, EPS which were isolated from L. plantarum YW11 reduced the production of the proinflammatory cytokines (TNFα, IL-1β, IL-6, IFN-γ, IL-12 and IL-18) and up-regulated IL-10, and this resulted in an amelioration of inflammatory bowel disease symptoms." (PMID 36769176, 2023).
inflammatory bowel disease (continued). "Furthermore, recent evidence suggests that the NLRP3 inflammasome and its maturation of IL-18 downregulates the IL-22 binding protein, an inhibitor of IL-22, which promotes cell repair in inflammatory bowel diseases." (PMID 24312491, 2013). "Here, we analyzed the potential role of gut bacteria and the hypoxia-inducible factor 1α (HIF1α) pathway in regulating mucosal IL18 expression in inflammatory bowel disease (IBD)." (PMID 38163085, 2023). "Studies have pointed the role played by IL-18 in Inflammatory bowel disease (IBD) by promoting intestinal homeostatic auto-inflammatory responses or protecting against the breach of pathogens through the epithelial barrier." (PMID 36032110, 2022). "Increased expression and bioactivity of IL-18 correlate with disease severity in inflammatory bowel disease (IBD) patients." (PMID 33910012, 2021). "The overexpression of IL-32 in a number of diseases including asthma, inflammatory bowel disease (IBD) and RA has been reported to be induced by IL-18." (PMID 25626592, 2015). "The heatmap of molecules participate in the “inflammatory bowel disease” revealed higher expression of NF-κB1, IFN-γ, IL18, IL1B, and IL18RAP in Group AOSC than in Group CD-AOSC." (PMID 41438472, 2025). "In inflammatory bowel disease and colorectal cancer, the NLRP1 inflammasome acts through IL-1β and IL-18." (PMID 39456655, 2024). "The results demonstrate that GSDMB interacted protein was significantly involved in cytokine–cytokine receptor interaction, sphingolipid metabolism, inflammatory bowel disease (IBD), and several immune pathways such as IL18/33 production, IFN-γ production, and inflammatory response." (PMID 37064151, 2023). "Previous studies have revealed that the high production of IL-1β and IL-18, through the dysregulation of inflammasome activity during the microbial invasion or intestinal inflammation, plays a critical role in the pathogenesis of inflammatory bowel diseases (IBD) and colorectal cancer." (PMID 34571825, 2021). "In patients with inflammatory bowel disease, a large population of inflammatory cells infiltrated in the mucosa, excessive inflammatory cytokines including tumor necrosis factor (TNF)-α, interleukin (IL)-18, IL-6, IL-1β were secreted." (PMID 33240089, 2020). "The NRLP inflammasome activated by ZEN is responsible for the maturation and secretion of proinflammatory cytokines IL-1β and IL-18, which play a role in the etiology of non-specific inflammatory bowel diseases." (PMID 32471145, 2020). "Research has confirmed that pro-inflammatory cytokines such as IL-1β, TNF-α, IL-18, along withsignaling molecules like MyD88 and NF-κB, play central roles in regulating inflammatory responses and have been established as core biomarkers in DSS-induced inflammatory bowel disease (IBD) models." (PMID 41227621, 2025). "Inflammasome-dependent mediators such as IL-1β, IL-18, and HMGB1 have been identified as potent promoters of intestinal pathology, which suggests that targeting these mediators may represent a useful therapeutic approach in inflammatory bowel disease (IBD)." (PMID 26355424, 2015).